MMP9 (matrix metallopeptidase 9)
Diseases named in the same sentence as MMP9 in open-access papers (continued):
Sharing a sentence is not in itself a finding about the gene and the disease.
oral cancer (continued). "In support of our results, P. gingivalis LPS has been shown to upregulate the expression of MMP2 and MMP9 in oral cancer cells." (PMID 36552854, 2022). "Gelatinases, including MMP-2 and MMP-9, are another subfamily of MMPs that is well-established as important markers in the malignant progression of oral cancer." (PMID 36330492, 2022). "In oral cancer, as the tumor progresses, high MMP9 expression is observed in tumor epithelium and stroma and relates to poor prognosis." (PMID 35008304, 2021). "Regarding the effective concentration, GLY extracts showed an inhibition of TNF-α level in oral carcinoma cells at more than 0.2 mg/mL, cell migration, and MMP-9 production in VSMCs at more than 0.125 mg/mL, and angiogenesis of HUVEC at 1.0–1.5 mg/mL." (PMID 33498415, 2021). "BME treatment led to an 8.1-fold downregulation of MMP9 compared to that in 4-NQO-induced oral cancer tissues (6.8-fold upregulation of MMP9)." (PMID 34572990, 2021). "By reducing NF-κB, MMP-2 and MMP-9 expression, anthocyanins can inhibit the metastasis of pancreatic and oral cancer." (PMID 34206588, 2021). "The down-regulation of MAPK8/JNK1 is reported to reduce human oral cancer cell migration by inhibiting MMP-9 enzymatic activity." (PMID 32703964, 2020). "Published reports show that MMP2 and MMP9 are upregulated in OSCCs, where they aid in the invasiveness of oral cancer cells, and silencing DSPP decreases oral cancer cell invasion." (PMID 32630820, 2020). "This study found that after treatment with SnO2 NP, both MMP-2 and MMP-9 protein and mRNA expressions in oral cancer cells were down-regulated by varying degrees." (PMID 32766221, 2020). "Various studies had shown the anti-metastatic effects of certain agent on NPC or oral cancers through the downregulation of MMP-2 or MMP-9 via the MAPK signaling pathways." (PMID 31850235, 2019). "To further clarify the anticarcinogenic effect of melatonin, we found that melatonin prevents the ANE-induced MMP-9 mRNA expression/secretion of oral cancer cells." (PMID 31831717, 2019). "Protective roles of MMP9 have also been identified in oral cancers depending on the stage of the disease." (PMID 27861153, 2017). "This study was the first to demonstrate that CAIX can promote oral cancer cell migration and invasion through MMP-9 expression." (PMID 29137326, 2017). "In this study, we found that CAIX overexpression induced MMP-9 expression and cell migration and invasion in human oral cancer cells." (PMID 29137326, 2017). "In conclusion, it can be inferred that CAIX overexpression induces MMP-9 gene expression, which consequently induces the metastasis of oral cancer cells." (PMID 29137326, 2017). "Thus, MMP-9 could be used as a diagnostic adjunct for early detection of oral cancer." (PMID 28160595, 2017). "Key words:Oral squamous cell carcinoma, oral cancer, saliva, salivary diagnostics, cancer detection, MMP-9, metalloproteinases." (PMID 28160595, 2017). "In summary, CAIX induces oral cancer cell migration and invasion by increasing MMP-9 expression, which is mediated through the phosphorylation of protein kinases (FAK/Src and ERK1/2) and the activation of AP-1 and NF-κB transcription factors." (PMID 29137326, 2017). "During oral cancer progression, Snail mediated TGFβ1-induced MMP-9 expression via upregulating Ets-126." (PMID 29259250, 2017). "Direct contact between saliva and the oral cancer makes measurement of salivary metalloproteinase- 9 (MMP-9) an attractive alternative." (PMID 28160595, 2017). "TCGA data sets revealed that the mRNA level of CAIX was significantly correlated with MMP-9 expression in oral cancer cells (r = 0.3035, p < 0.0001)." (PMID 29137326, 2017). "This study revealed that melatonin inhibits the TPA-induced MMP-9 expression of oral cancer HSC-3 and OECM-1 cells through ERK1/2 phosphorylation." (PMID 26980735, 2016). "Our results indicated that MMP-9 is a critical target of melatonin for regulation of oral cancer metastasis." (PMID 26980735, 2016).
oral cancer (continued). "The DNMT3b silencing vectors induced an increase in E-cadherin and decreases in VEGF and MMP-9 in oral cancer cells." (PMID 24625449, 2014). "In a clinical setting, the expression of MMP2 and MMP9 has appeared to be closely related to metastasis in oral cancer." (PMID 25330185, 2014). "As the CCL5-CCR5 axis has been shown to promote the motility of human oral cancer cells in vitro and to induce the expression of MMP9, we also examined the effect of rCCL5 on MMP9 expression levels in HSC-3 and SAS as well as in dysplastic DOK cells." (PMID 24204919, 2013). "Early metastasis is a critical step for oral carcinogenesis and the overexpression of MMP-9, and extracellular matrix metalloproteinase leads to a poor prognosis of oral cancer." (PMID 23710144, 2013). "Elevated MMP-2 and MMP-9 expression have been observed in invasive and metastatic cases of human oral cancer." (PMID 23799155, 2013). "Accordingly, the TGFβ1/Smad 2/3 axis regulates MMP-9 expression through the transcriptional factors Snail and Ets-1, contributing to oral cancer progression." (PMID 20462450, 2010). "Levels of MMP9 protein are higher in saliva of patients with oral cancer compared with healthy controls, and this could be a potential biomarker for OSCC early detection." (PMID 41385756, 2026). "Thus, when 4-carbomethoxyl-10-epigyrosanoldie E inhibits RhoA expression, this leads to a decrease in MMP-2 and MMP-9 levels, impacting the migration and invasion of Cal-27 and Ca9-22 oral cancer cells." (PMID 38374934, 2024). "Consequently, this results in decreased levels of MMP-2, MMP-9, and uPAR proteins, curtailing the migratory and invasive capabilities of these oral cancer cells." (PMID 38374934, 2024). "In addition, due to the critical roles of MMPs in tumor cell invasion and metastasis, MMPs such as MMP2 and MMP9 have been identified as prognostic factors for many types of cancer, such as head and neck squamous cell carcinomas (HNSCCs) and oral cancers." (PMID 35203529, 2022). "Our hypothesis is additionally supported by ChIP-Seq data demonstrating JUNB binding to and acting as a repressor on the MMP9 promoter in oral cancer." (PMID 34282521, 2021). "Regarding the oxidative stress biomarkers, our results did not illustrate the existance of an enhanced redox stress following lutein and lutein Nps treatment of oral cancer cells which, probably, represents one of the reasons that triggered MMP-9 downregulation." (PMID 34072756, 2021). "MMP-9 knockdown inhibits oral cancer cell invasion and metastasis not only by inhibiting OSCC cell proliferation, migration, and vascular endothelial cell adhesion and angiogenesis but also by inhibiting other tumor metastasis-related factors, such as RhoC and Src genes." (PMID 33828938, 2021). "CCL5 enhances oral cancer cell migration through the increase in MMP-9 production." (PMID 32961854, 2020). "Therefore, a low concentration of WFA has the potential to inhibit the MMP-2 and MMP-9 activities in order to inhibit migration or metastasis of oral cancer cells." (PMID 32429564, 2020). "Moreover, the expression of cyclin-D1, Bcl-2, and MMP-9 were upregulated and caspase-9 was downregulated, which are the key molecules involved in oral cancer cell proliferation, survival, invasion, and migration." (PMID 29996471, 2018). "Oral cancer patients with high MMP-9 and CRP levels have had worse prognosis." (PMID 29929486, 2018). "MMP-2 and MMP-9, which are secreted by invasive cancer cells, play important roles in cancer cell invasion and metastasis because tumor cells must cross the type IV collagen-rich basement of vessel walls to spread to other sites during oral cancer metastasis." (PMID 30143678, 2018). "Collectively, VEGF, PCNA and MMP9 may modulate the proliferation, migration, and invasion of oral cancer cells under the regulation of SYK." (PMID 29137391, 2017). "CTFs were recently found required for inducing MMP-9 in oral carcinoma cells." (PMID 27737648, 2016).
oral cancer (continued). "In addition, the expression of both MMP-2 and MMP-9 was significantly decreased in the KB oral cancer cells that had been co-stimulated with berberine and the p38 MAPK-specific chemical inhibitor compared to those that had been treated with berberine only." (PMID 25634589, 2015). "Therefore, we found that downregulation of MMP-9 in oral cancer cells by CTXIII treatment was helpful to therapeutic effect of oral cancer." (PMID 23710144, 2013). "For example, the levels of MMP-2 and MMP-9 proteins were related to invasion of oral cancer." (PMID 23710144, 2013). "Polymorphisms in the MMP9 gene allele are associated with an increased risk of developing the initial stages of oral cancer among patients without a family history of cancer and high smoking and/or alcohol use." (PMID 23365550, 2013). "Contrary to earlier models, recent studies show that MMP-9 plays a protective role in oral cancers." (PMID 23365550, 2013). "However, the philosophy of oral carcinoma progression has become significantly more complicated; now, MMP-9 is known as a multifunctional modulator that is involved in very complex cell-signaling cascades." (PMID 23365550, 2013). "Furthermore, MMP-9 rs3918242 was related to BC, GC, HCC, LC, and oral cancer risk." (PMID 35574300, 2022). "Finally, it was revealed that MMP-9 rs3918242 under the allelic and recessive models was remarkably related to oral cancer incidence among the overall populations (allelic model, OR = 1.309, 95% CI = 1.078–1.589, p = 0.007; recessive model, OR = 3.497, 95% CI = 1.812–6.749, p < 0.001)." (PMID 35574300, 2022). "Additionally, in oral cancer, monocytes can take up extracellular vesicles, which promote the activation of NF-κB and the establishment of a proinflammatory milieu marked by increased levels of IL-6 and matrix metallopeptidase 9 (MMP9)." (PMID 31467934, 2019). "Mechanistically, uptake of EVs derived from oral cancer cells by monocytes caused activation of the inflammatory pathway, NF-κB activation, and establishment of a pro-inflammatory and pro-tumorigenic milieu marked by increased levels of IL-6, CCL2, PEG2 and MMP9 levels." (PMID 30410681, 2018). "MMP-9, also known as gelatinase-B and 92 kDa type IV collagenase, is responsible as other metalloproteinases for the degradation of the environmental barriers, such as extracellular matrix and basement membrane, and is reportedly involved in the oral cancer invasion process." (PMID 29619127, 2018). "Therefore, we hypothesise that melatonin inhibits TPA-induced MMP-9 expression in oral cancer cells by regulating the coactivator family through the ERK1/2 signalling pathway." (PMID 26980735, 2016). "Therefore, the role of MMP-9 is complicated and may fluctuate throughout the different types and stages of oral cancers." (PMID 23365550, 2013). "With the use of bioinformatics analysis of the gene expression profile of metastatic and non-metastatic lymph nodes and original tumors, we identified a novel oral cancer metastatic gene signature, FN1, CXCL8, and MMP9." (PMID 37640804, 2023). "Oral cancer cell migration and invasion can be encouraged by elevated MMP-2 and MMP-9 expression and activity." (PMID 38068849, 2023). "MMP-7 is mainly expressed in the invasive portion of oral cancer, whereas MMP-8 and MMP-9 are mainly detected in peritumoral inflammatory cells." (PMID 36275775, 2022).
oral cancer (continued). "In oral cancer cells, treatment with GDF-11 stimulates cell migration and induced expressions of MMP2 and MMP9." (PMID 35705978, 2022). "Research on the oral cancer cells and tissue of OSCC patients suggests that MMP-2 and MMP-9 are frequently seen to promote infiltrative growth and bone resorption." (PMID 36011038, 2022). "In OSCC, the expression of MMP9 and MMP2 in tumor and stromal cells defined the invasiveness of oral cancer." (PMID 35008304, 2021). "Moreover, MMP-9 may be an indicator for early diagnosis of oral cancer (OC)." (PMID 33735248, 2021). "Anthocyanins from a species of black rice can suppress the in vitro migration and invasion of human oral cancer CAL 27 by reducing MMP-2, MMP-9, and NF-kB p65 expression through the suppression of the PI3K/Akt pathway and inhibition of NF-kB expression." (PMID 34206588, 2021). "Mechanically, this safe treatment of WFA inhibits MMP-2 and MMP-9 activities and induces antioxidant gene expression as well as MAPK activation in oral cancer cells." (PMID 32429564, 2020). "In agreement with the inhibitory effect on MMP-9 activity, we further found that low concentration of WFA (>95% viability) exhibits inhibitory effects on MMP-2 activity in oral cancer Ca9-22 cells." (PMID 32429564, 2020). "Quercetin efficiently inhibits the cellular migration and invasion of the HNSCC cell lines, HSC-3 and FaDu, and human oral cancer cells (SAS) via suppression of the MMP-2 and MMP-9 activation." (PMID 32486484, 2020). "F. nucleatum can induce the production of various matrix metalloproteinases (MMPs), such as MMP-9 and MMP-13, which have been used in monitoring and detecting metastatic phenotypes in oral cancer." (PMID 31993418, 2019). "In an oral cancer model, decorin was aberrantly expressed in the cancer cells, and knockdown of decorin reduced angiogenic mediators, including VEGF and MMP9, and decreased angiogenesis." (PMID 28290552, 2017). "Examinations on clinical samples exhibited that MMP-9, CREBBP, and EP300 were significantly increased in oral cancer tissues." (PMID 26980735, 2016). "In the present study, we demonstrated that berberine suppressed the migration of KB oral cancer cells through the downregulation of both MMP-2 and MMP-9." (PMID 25634589, 2015). "The results of this study show that Selaginellatamariscina reduced oral cancer migration and invasion by inhibiting MMP-2 and MMP-9 gene expression, and enzyme activity." (PMID 23799155, 2013). "Our results showed that Selaginellatamariscina halted oral cancer cell migration through the down-regulation of MMP-2 and MMP-9 expression and by decreasing DNA-binding activity to promoter elements." (PMID 23799155, 2013). "Involvement of S100A14 in the regulation of oral cancer cell proliferation and invasion, by modulating expression of several molecules including p21, MMP1 and MMP9, was reported by our recent studies." (PMID 24086685, 2013). "In a model of oral cancer, resveratrol suppressed the metastasis and invasion of H-357 cells by inhibiting the activity of MMP-2 and MMP-9 and numerous inflammation mediators, e.g., NF-κB, COX-2, inducible nitric oxide synthase (iNOS), TLR4, TNF-α, interleukin-1 β (IL-1 β), and interleukin-6 (IL-6)." (PMID 39335164, 2024). "Furthermore, in a study on the progress and invasion of oral cancer, the author also used a co-IP experiment to prove the interaction between TIMP1 and MMP9." (PMID 36800936, 2023). "Furthermore, the depletion of CRT from oral cancer cells resulted in the decreased activity of matrix metalloproteinase-2 (MMP-2) and MMP-9, possibly due to the downregulation of the FAK-ERK-MMP-2/MMP-9 signaling pathway." (PMID 37979915, 2023).
oral cancer (continued). "Another study reported that the overexpression of FABP5 in oral cancer cells enhances cell proliferation and invasiveness by increasing the expression of MMP-9, while the knockdown of FABP5 using shRNA significantly inhibits the activity of MMP-9." (PMID 35445019, 2022). "Accordingly, WFA inhibits migration of oral cancer cells by inactivating MMP-2 and MMP-9." (PMID 32429564, 2020). "In this study, PBL extract and one major PBL component - HC (at non-toxic concentrations) prevent the ANE-induced MMP-9 production in oral cancer epithelial cells, suggesting attenuation effects to cancer invasion and metastasis." (PMID 31831717, 2019). "Moreover, cyclin-D1, Bcl-2, and matrix metalloproteinase-9 (MMP-9) were upregulated, and caspase-9 was downregulated, suggesting that silencing of NGAL increases oral cancer cell proliferation, survival, and migration." (PMID 29996471, 2018). "A recent study found that MMP-9 level in oral carcinoma cells was reduced to the normal level with lack of the cytoplasmic domain of N-cadherin, which suggests a vital role for CTFs of N-cadherin in regulating MMP-9." (PMID 27737648, 2016). "Therefore, overexpression of MMP-2 and MMP-9 may serve as indicators of metastatic phenotype, suggesting that monitoring changes in MMP expression following treatment could be a valuable marker for assessing treatment outcomes in patients with oral cancer." (PMID 39408625, 2024).